S100A4 (S100 calcium binding protein A4)
Diseases named in the same sentence as S100A4 in open-access papers (continued):
Sharing a sentence is not in itself a finding about the gene and the disease.
tumor (continued). "Conversely, the released S100A4 protein induces the upregulation of fibronectin (FN) in fibroblasts and a number of cytokines, including RANTES in tumor cells as well as stimulates cell motility in a wound healing assay." (PMID 20442771, 2010). "The resulting tumours were characterized by increased development of extracellular matrix, as well as an increase of murine S100A4 concentration and activity of MMP-2 in the tumour interstitial fluid." (PMID 20723242, 2010). "In these S100A4-positive PTC samples, stronger staining was often observed at the tumour-invading front as compared to the central region." (PMID 16265347, 2005). "RP11-54O7.17 was also found to be differentially expressed in different macrophages in TNBC, and S100A4 was also found to play a role in tumor immunity, thus the interaction of RP11-54O7.17 with other signaling pathways and its role in the tumor microenvironment need to be further explored." (PMID 41173847, 2025). "Similarly, T cell accumulation was also reduced by genetic depletion of S100a4 in stromal cells in MMTV-PyMT and CSML100 tumor bearing mice." (PMID 40078995, 2025). "Although this blocking effect did not affect Arg1 expression in TMZ-resistant GBM tumor, blocking IL-19 still can downregulate the expression of STAT3-associated immunosuppressive genes (CD274 and S100A4) in both TMZ-sensitive and TMZ-resistant GBM tumor." (PMID 40057744, 2025). "In addition, the expression of pro-tumor indicators in macrophages (VEGF, MMP9, TGF-β, and HIF-1α) was also higher in S100a4-OE MH-S." (PMID 40658605, 2025). "The elevated lactate levels in tumor cells expressing ALDH1A1 and S100A4 from the resistant group, along with the increased expression of ALDH1A1, suggest that lactylation is integral to the development of drug resistance, resulting in a higher accumulation of lactate products in this group." (PMID 40093000, 2025). "We discovered that both S100A4 and CAF-CM cells could stimulate tumor cells to highly express the PD-L1, a known immunosuppressive marker." (PMID 40772225, 2025). "That is, the upregulation of TGFβI and S100A4 helps enhance the oxidative stress damage of HCC cells and maintain the integrity of mitochondrial function, thereby accelerating cell proliferation and promoting tumour development." (PMID 40821652, 2025). "The expression of VEGFA in the xenograft tumor also revealed that sh-ANXA9 and sh-S100A4 could decrease the expression of VEGFA." (PMID 38609357, 2024). "This anatomical distinction may also play a role in modulating the expression and function of S100A4 and S100A14, thereby affecting tumor behavior and progression differently depending on the site of origin." (PMID 39205741, 2024). "Extracellular S100A4 can be crosslinked directly by TG2 and the S100A4 polymers then activate the syndecan-4/PKCα/α5β1 integrin signaling pathways, which promoted tumor cell migration and metastasis." (PMID 39544364, 2024). "Low FSP/S100A4 expression has been correlated with improved disease free survival, while data showed high nuclear S100A4 expression correlated with worse overall survival; however, these studies do not differentiate between CAF and tumor S100A4 expression." (PMID 38525245, 2024). "Tumor cells (n=38284; 31.2%, n=8; range 22.5-37.2% per PDAC) were annotated into 7 different subtypes, based on the expression of Pan-Ck, cytokeratin 7 (Ck-7), CD44, S100A4, PTX3, CA-IX, CD74." (PMID 39575252, 2024). "This article aims to explore the complex interplay between S100A4 and S100A14 in CRC progression, with a particular focus on how their expression and function may vary according to the anatomical location of the tumor." (PMID 39205741, 2024).
tumor (continued). "The expression of VEGFA in the xenograft tumor also revealed that sh-ANXA9 and sh-S100A4 could decrease it." (PMID 38609357, 2024). "Tumor cells exhibited a strong nucleolar positive expression of S100A4, with no apparent cytoplasmic staining." (PMID 39591300, 2024). "This may partially explain why knocking out SEMA6B, MT1E, S100A4, or ASAH2 may significantly promote tumor colony growth." (PMID 39605490, 2024). "MACC1 is a tumor-initiating and metastasis-promoting oncogene, whereas S100A4 has not been shown to initiate tumor formation but can, nevertheless, promote malignant tumor growth and metastasis formation." (PMID 36674695, 2023). "S100a4 activates the RAGE pathway, which is known to enhance tumor growth and metastasis." (PMID 36973439, 2023). "The MC38 and Pan02 tumors showed no evident differences in tumor cell morphologies between S100a4-Cre; Ext1f/f and control mice." (PMID 36809261, 2023). "Since S100A4 may be derived from NETs, future research must ascertain whether inhibiting NET production normalizes the tumor vasculature and constitutes a potential anti-angiogenic cancer treatment strategy." (PMID 36873885, 2023). "In addition, correlations were also noted in the tumor array between S100A11 and S100A2 (R = 0.54), S100A4 (R = 0.46), S100A6 (R = 0.49), S100A13 (R = 0.67), S100A14 (R = 0.65), and S100A16 (R = 0.78)." (PMID 37627239, 2023). "For example, the amplification of S100A4 and the amplification of KRT81 exhibit a co-occurrence relationship in both clusters, indicating that they have a common impact on tumor development and that there is a potential concomitant occurrence between the two genes." (PMID 37238637, 2023). "Moreover, evidence shows that the S100A4-mediated EMT displays a key role in tumor development and non-tumor pathophysiology." (PMID 37873538, 2023). "As a result, we found that CD163, CD74, S100A4, S100A12, HLA-DRA, and HLA-DRB1, which are usually highly expressed in myeloid cell, were also highly expressed in tumor cells of cluster 6; thus, we termed this cluster myeloid-like tumor cells." (PMID 37138326, 2023). "Perhaps this specific effect of S100a4 could be due to its extracellular attachment to chromatin, which may increase the avidity of S100a4 signaling through RAGE on nearby tumor cells." (PMID 36973439, 2023). "S100A4, a calcium-binding protein that plays an important role in promoting cancer progression as well as the pathophysiological development of various non-tumor diseases, has not been explored in Mtb-infected hosts." (PMID 37628889, 2023). "Unlike MC38 tumors, the intensity of Alcian blue staining in the peri-tumor region was not apparently different in S100a4-Cre; Ext1f/f and control mice." (PMID 36809261, 2023). "However, in the tumor array, positive correlations were observed between S100A14 and S100A2 (R = 0.50), S100A4 (R = 0.55), S100A6 (R = 0.45), S100A7 (R = 0.47), S100A11 (R = 0.65), S100A16 (R = 0.57) and S100P (R = 0.66)." (PMID 37627239, 2023). "To test whether MACC1-dependent expression of S100A4 is a clinically prevalent phenomenon in CRC, we detected both markers by IHC in representative tumor sections from a previously published cohort." (PMID 36008464, 2022). "Compared to the control medium, the culture medium collected from DOX-treated tumour cells upregulated ZIP1 expression in fibroblasts, which could be reversed by anti-S100A4 antibody." (PMID 36207295, 2022). "Upon co-transplantationof tumor cells and fibroblasts with the S100A4– phenotypein syngeneic mice, no metastases were formed, however,upon transplantation of S100A4+ fibroblasts, the metastaticpotential of tumor cells returned." (PMID 35342854, 2022).
tumor (continued). "Together with S100A4, S100A6 is the most widely documented protein in the S100 family and is a potential biomarker of tumor invasiveness in proteomics in MM and other cancers, and their combined involvement in breast cancer cell proliferation and motility was recognized early." (PMID 35873564, 2022). "For example, it has been proposed that intracellular S100A4 aids with the organization of the cytoskeleton by modulating the function of non-muscular myosin-IIa filaments (NM-IIA) and thus influencing cell motility also in tumor tissues." (PMID 35326507, 2022). "Because S100A4 can abrogate the actin-dependent ATPase and polymerization activity of NMIIA, S100A4 may serve as a critical regulator of tumor migration, in line with the idea that NMIIA acts as an inhibitor of cell migration." (PMID 35392912, 2022). "This is likely stimulated by extracellular VEGF that is released by S100A4(+)/HIF-1α(+) tumor cells in non-Ps perinecrotic lesions." (PMID 35392912, 2022). "Finally, strong S100A4(+)/GFAP(+) GBM cells showed vessel co-option, where tumor cells migrate along the preexisting vessel, around both small- and mature vascular structures with strong SMA(+) vascular components in the vascular-rich area." (PMID 35392912, 2022). "Grum-Schwensen B., Klingelhofer J., Berg C.H., El-Naaman C., GrigorianM., Lukanidin E., Ambartsumian N. Suppression of tumor developmentand metastasis formation in mice lacking the S100A4(mts1)gene." (PMID 35342854, 2022). "The involvement of S100A4 in EMT and MM has been previously documented in a large collection of 109 tumor specimens from patients, showing its specific high expression in the sarcomatoid histological subtype, together with vimentin and ZEB1, linked to aggressive features." (PMID 35873564, 2022). "In this case, we determined a significant difference for S100A4 and MRC2, detecting an increased expression of both molecules for the tumor group, but conclusive results could only be obtained for MRC2." (PMID 36613987, 2022). "It is interesting to note that this analysis did not indicate any predicted activation relationships; rather, relationships related to inhibition (for seven proteins: LMNA, NME1, PKM, S100A4, SERPINA1, VIM, and AHCY) were indicated for both increased and decreased proteins in the tumor." (PMID 35512017, 2022). "Another explanation could be that the role of S100A4 on migration is different in the context of the tumor source, i.e., FLO1 is derived from a primary tumor while NCI-N87 cells originate from a metastasis." (PMID 35326507, 2022). "S100A4+ MAFs promote angiogenic microenvironment establishment in support of metastatic colonization by providing vascular endothelial growth factor-A (VEGF-A), while the ablation of S100A4+ CAFs does not affect angiogenesis at the primary tumor site." (PMID 34112258, 2021). "As reported with S100A4, hypoxia regulates S100A8/A9 expression through the presence of an HRE in the promoter region of both S100A8 and S100A9 genes, suggesting that these two proteins contribute to tumor progression in hypoxic conditions." (PMID 34360919, 2021). "Based on the positive correlation between the frequencies of S100A4+ TAMs and tumor growth without chemotherapy, next, we investigated the effects of S100A4+ TAMs on tumor growth after chemotherapy using paired S100A4WT and S100A4KO Raw264.7 cells." (PMID 34145030, 2021). "Significantly inhibited tumor development (tumor growth and weight) and a lower proportion of CD206+ protumor TAMs was observed in the macrophagic-specific S100A4-KO animals and in the animals treated with PPAR-γ inhibitor compared with control animals, in which no body weight change was observed." (PMID 34145030, 2021). "In addition, miR-765 mimics obviously down-regulated the expression of several EMT-related markers (e.g., COL3A1, FN1, CDH2, S100A4, MMP9, SNAIL and ZEB1) and up-regulated TJP1 expression in tumor lesions." (PMID 33859750, 2021).
tumor (continued). "Unlike α-SMA, S100A4 was expressed mainly in single cells distributed throughout the tumor, with only some degree of co-localization with α-SMA." (PMID 33311552, 2021). "IHC staining revealed that fibroblasts, lymphocytes, and macrophages expressed S100A4 in the UIP area, and the stroma and fibrosis in the primary tumor expressed S100A4, whereas tumor cells did not." (PMID 34078355, 2021). "Without treatment, tumor growth was remarkably inhibited when proliferating S100A4+ cells were ablated by GCV treatment." (PMID 34145030, 2021). "Not surprisingly, a number of proteins involved in tumor cell dissemination and BBB invasion were also found to associate with BCBM progression, including cathepsin-S, S100A4, RANKL, RANK, Src, HYAL1, HAS2 and prominin-1 (CD133)." (PMID 32110283, 2020). "Likewise, increasing expression of S100A4 is often related to pathological disorders including metastasis formation, epithelial–mesenchymal transition (EMT), and tumor outgrowth." (PMID 33117687, 2020). "We also found a positive correlation (r2 = 0.55) between the mRNA expression of S100A4, a gene that reflects the inflammatory function of CAFs and COL1A2, a gene reflecting their effect on the stiffness of the tumor ECM, suggesting that these two functions of CAFs are closely associated." (PMID 33114328, 2020). "Further, S100A4 is capable of activating the phosphoinositide 3-kinase/Akt/mechanistic target of the rapamycin pathway (PI3K/Akt/mTOR), leading to increased levels of VEGF and decreased E-cadherin, which triggers tumour progression and cell migration." (PMID 32722137, 2020). "This suggests that despite increased S100A4 expression, tumor metastasis was de facto not enhanced but even decreased with plasma treatment as the motility data show." (PMID 32917026, 2020). "In the same study, the authors reported that the interaction of S100A4 with RAGE resulted in prometastatic activation of A375 cells, with decreased cellular adhesion to fibronectin, increased cell motility, invasiveness, and tumor growth." (PMID 33256110, 2020). "Thus, photostress-induced NO signaled for altered status of several key tumor promoting proteins: MMP-9 (activation), TIMP-1 (downregulation), Survivin (upregulation), and S100A4 (upregulation)." (PMID 33073206, 2020). "S100A4 also induces the secretion of further paracrine factors, such as IL-8 and CCL2, which in return, promote angiogenesis and recruitment of monocytes, creating an inflammatory milieu in the tumour microenvironment." (PMID 32722137, 2020). "Upregulated expression of S100A4 and ACKR3 was detected in Doc-resistant tumor samples." (PMID 31895690, 2019). "Moreover, western blotting and immunohistochemistry revealed altered expression of S100A4, ACKR3 and CDH1in clinical tumor samples." (PMID 31895690, 2019). "S100A4 plays important roles in tumor metastasis, but its role in regulating autophagy has not been well characterized." (PMID 29449540, 2018). "In the context of pancreatic cancer, lineage tracing studies revealed fibroblast‐specific protein‐1 (Fsp1, also called S100A4), Zeb1, and Snail‐expressing cancer cells, defined as cancer cells exhibiting a partial EMT program, were observed early in tumor formation." (PMID 30120146, 2018). "S100A4 is secreted from both tumor and non-malignant cells and exerts extracellular effects in regulating angiogenesis and cell migration." (PMID 29449540, 2018). "As our study has demonstrated, too, the exaggerated expression of the S100A4 protein indicates the capacity of the tumor for invasion and metastasis rather than the capacity for initiating a tumor formation." (PMID 30111999, 2018). "Changes in tumor burden independent of the presence of S100A4 in the implanted tumor cells implied that host S100A4 is predominantly involved in inhibiting tumor growth in S100A4−/− mice." (PMID 29556233, 2018).
tumor (continued). "Extracellular S100A4 stimulates the production of MMP13 in endothelial cells and promotes tumor angiogenesis by the induced secretion of pro-inflammatory cytokines in tumor cells in the tumor microenvironment." (PMID 29069865, 2017). "A study has indicated that the S100A4-mediated epithelial–mesenchymal transition (EMT) program plays a vital role in the occurrence and development of various diseases, including tumor and non-tumor diseases." (PMID 29204268, 2017). "Downregulation of NudCD1 in tumor cells that showed a high expression of the protein resulted in a down-regulation of some oncogenic genes such as CTSL, MMP15, uPAR, VEGF, COX-2, S100A4, MUC1, MDM2 and RAC110 and an increase of the resistance to 5-fluorouracil-induced apoptosis." (PMID 29021621, 2017). "S100A4 siRNA was able to significantly decrease proliferation, induce apoptosis, and inhibit the invasive potential of anaplastic thyroid cancer (ATC) cells in vitro, and abdominal cavity metastasis and tumor growth in vivo." (PMID 29069865, 2017). "Elevated S100A4 expression leads to the development and progression of many non-tumor diseases, indicating that targeting of S100A4 expression or activities is a novel strategy for treating non-tumor pathologies." (PMID 29204268, 2017). "Of the 929 tumor samples present on the TMA, 146 cases were not evaluable for technical reasons or because no tumor tissue was present, leaving 783 cases available for S100A4 analysis." (PMID 27273130, 2016). "Proteomic analysis of MDCKYBX1 tumour xenografts revealed 428 proteins identified in MDCKYBX1 tumour xenografts, and EMT markers (VIM, FN1 and S100A4) and proteins involved in cancer progression (H-Ras and CLU) were identified." (PMID 25980435, 2015). "One limitation is that the effects of gain of S100A4 in vivo in tumor progression have not been specifically tested, and future studies are necessary to understand the effects of gain of S100A4 in tumor progression in vivo." (PMID 25677816, 2015). "S100A4 can be secreted, and several lines of evidence suggest that it can induce cytokine networks, such as those mediated by the inflammatory cytokines IL8, CCL2 and SAA, thereby enabling tumor cells to engage with angiogenic and inflammatory stromal cells." (PMID 25310523, 2014). "S100A4 and ANXA2 binding promotes invasion and signal transduction in tumor cells." (PMID 25362534, 2014). "Although these slight differences in expression levels could be seen, we conclude that the differential expression of S100A4 and S100A9 in splenic CD11b+ cells remains also during inflammatory disease or tumor challenge." (PMID 23667563, 2013). "We found that S100A4 expression in the invasive margin was increased in infiltrative tumors, those with a lymph node metastasis, advanced AJCC stage, or lymphovascular- and perineural invasion, which are all parameters representing tumor aggressiveness." (PMID 23783026, 2013). "Interestingly, S100A4 and S100A9 are expressed by distinct CD11b+ subpopulations both in healthy animals and in animals with either inflammatory disease or tumor burden." (PMID 23667563, 2013). "Although the presence of intracellular S100A4 does not affect tumor cell proliferation we demonstrated the secretion of S100A4 in cell lines expressing this protein." (PMID 24023743, 2013). "Although no increased tumor formation was found in S100A4 transgenic mice, metastasis formation was highly promoted, when crossed with mice that form tumors spontaneously." (PMID 22878175, 2012). "Importantly, a significant association was also found between expression of S100A4 and ephrin-A1 in primary tumor samples from NSCLC patients, indicating that S100A4 stimulates ephrin-A1 expression both in vivo and in vitro." (PMID 22853000, 2012). "On the contrary, circulating S100A4 is not suitable as an ideal tumor marker, since red blood cells and mononuclear cells also contain S100A4." (PMID 23166536, 2012).